COMMD7 (COMM domain containing 7)
Description:
Scaffold protein in the commander complex that is essential for endosomal recycling of transmembrane cargos; the commander complex is composed of the CCC subcomplex and the retriever subcomplex. May modulate activity of cullin-RING E3 ubiquitin ligase (CRL) complexes. Associates with the NF-kappa-B complex and suppresses its transcriptional activity.
Synonyms: C20orf92; dJ1085F17.3
Tractability: PROTAC: ubiquitination databases record sites on it; its protein half-life has been measured.
Gene: Protein-coding gene on chromosome 20 (32,702,648 to 32,743,928, reverse strand). Ensembl gene ENSG00000149600.
Subcellular location: Cytoplasmic vesicle
Subcellular location (Human Protein Atlas): Vesicles
Pathways (Reactome):
Metabolism of proteins: Neddylation
Gene Ontology:
Molecular function: NF-kappaB binding; protein binding
Biological process: negative regulation of DNA-templated transcription; tumor necrosis factor-mediated signaling pathway; endocytic recycling
Cellular component: protein-containing complex; endoplasmic reticulum membrane; endosome membrane; cytoplasmic vesicle
Genetic constraint (gnomAD): Loss-of-function variants: 28 observed, 33.46 expected, observed/expected ratio (o/e) 0.84, 90% interval 0.62 to 1.15. The upper end of that interval is the gene's LOEUF score, 1.15, which puts it in group 5 of 6, group 1 being the genes least tolerant of losing a copy. Missense variants: 209 observed, 233.68 expected, observed/expected ratio (o/e) 0.89, 90% interval 0.8 to 1. Synonymous variants: 80 observed, 83.28 expected, observed/expected ratio (o/e) 0.96, 90% interval 0.8 to 1.16.
Homologues: Orthologues: chimpanzee COMMD7 (100% identical), dog COMMD7 (96% identical), pig COMMD7 (96% identical), guinea pig COMMD7 (91% identical), macaque COMMD7 (88% identical), mouse Commd7 (88% identical), rat Commd7 (82% identical), zebrafish commd7 (61% identical). Paralogues in human: COMMD6 (12% identical), COMMD8 (12% identical).
Diseases named in the same sentence as COMMD7 in open-access papers:
COMMD7 is named in the same sentence as 21 diseases in open-access papers, as found by Europe PMC text mining. Sharing a sentence is not in itself a finding about the gene and the disease. The quoted sentences say what the papers report.
hepatocellular carcinoma (11 papers, 2012 to 2024). A malignant tumor that arises from hepatocytes. "COMMD7 is a newly identified gene overexpressed in hepatocellular carcinoma (HCC) and associated with tumor invasion and poor prognosis." (PMID 23049798, 2012). "In contrast, the high expression of COMMD7 stimulated the proliferation and invasion of hepatocellular carcinoma and pancreatic ductal adenocarcinoma." (PMID 36776284, 2023). "No information exists on the specific role of COMMD7 in BC but data exist revealing that COMMD7 expression levels are upregulated in hepatocellular carcinoma tissues and pancreatic ductal adenocarcinoma (PDAC) tissues and cell lines." (PMID 34063128, 2021). "Studies in several tumors such as hepatocellular carcinoma and pancreatic ductal adenocarcinoma have evaluated the expression and function of COMMD7 in tumor development." (PMID 33891561, 2021). "COMMD7 inhibits tumor growth in liver and kidney cancers but can act as a carcinogen in hepatocellular carcinoma." (PMID 34943955, 2021). "It is reported that COMMD7 plays a role in a novel NF-κB-positive feedback loop by dual-directional regulation in hepatocellular carcinoma (HCC)." (PMID 32373154, 2020). "Here, we examined the expression of COMMD7 and NF-κB in patients with hepatocellular carcinoma, and analyzed the correlation between COMMD7 and NF-κB." (PMID 27129158, 2016). "Compared to HL7702 human liver cells, HepG2, SMMC-7721, Huh7 and Hep3B human hepatocellular carcinoma cells expressed higher level of COMMD7, and COMMD7 mRNA." (PMID 27129158, 2016). "Then, HepG2 and SMMC-7721 cells were used as cell models to investigate the role of COMMD7 in hepatocellular carcinoma." (PMID 27129158, 2016). "To investigate the role of COMMD7 in hepatocellular carcinoma, we compared the difference in expression of COMMD7 between hepatocellular carcinoma and para-carcinoma tissues using immunohistochemistry (IHC), qRT-PCR and Western Blot assays." (PMID 27129158, 2016). "Then, we detected the expressions of COMMD7 in human hepatocellular carcinoma cell lines and found that it was significantly upregulated inHepG2 and SMMC-7721 cells." (PMID 27129158, 2016). "Taken together, these results suggest that COMMD7 is a NF-κB target gene in hepatocellular carcinoma cells, and NF-κB directly correlates with COMMD7." (PMID 27129158, 2016). "Here, we aimed to investigate the correlation between nuclear factor-kappa B (NF-κB) and COMMD7 in hepatocellular carcinoma." (PMID 27129158, 2016). "IHC revealed that the staining of COMMD7 and p65 were differentially distributed between hepatocellular carcinoma and para-carcinoma tissues." (PMID 27129158, 2016). "The correlation between nuclear factor-kappa B (NF-κB) and COMMD7 in hepatocellular carcinoma (HCC) development remained unclear." (PMID 27129158, 2016). "The expression levels of COMMD7 inhepatocellular carcinoma were much stronger than the para-carcinoma tissues, which suggests that COMMD7 is involved in the pathological changes of hepatocellular carcinoma." (PMID 27129158, 2016). "This suggests that COMMD7 is correlated with a novel NF-κB positive feedback loop in hepatocellular carcinoma." (PMID 27129158, 2016). "Furthermore, silencing of COMMD7 inhibits hepatocellular carcinoma (HCC) cell proliferation, migration, and invasion by suppressing NF‐κB p65,21 thereby acting as a new molecular target in the late stages of pancreatic ductal adenocarcinoma." (PMID 36205192, 2023). "COMMD7 acts as an oncogene increasing metastatic properties of hepatocellular carcinoma." (PMID 34943955, 2021). "Finally, the roles of NF-κB and COMMD7 in cell proliferation, cell apoptosis, migration and invasion of hepatocellular carcinoma cell lines, and the tumor growth were studied." (PMID 27129158, 2016). "Another study revealed that COMMD7-overexpressed hepatocellular carcinoma (HCC) cells promoted the proliferation of naïve HCC cells." (PMID 33891561, 2021).
hepatocellular carcinoma (continued). "Thus, COMMD7 is correlated with a novel NF-κB positive feedback loop in hepatocellular carcinoma." (PMID 27129158, 2016). "NF-κB and COMMD7 transcriptional activity appear to play important roles in driving the progression of hepatocellular carcinoma (HCC), especially in tumor progression." (PMID 27129158, 2016). "Also, COMMD7 has been reported to be upregulated in hepatocellular carcinoma (HCC) and promote HCC cell proliferation." (PMID 33273919, 2020).
pancreatic ductal adenocarcinoma (5 papers, 2020 to 2024). An infiltrating adenocarcinoma that arises from the epithelial cells of the pancreas. "COMMD7 is overexpressed in pancreatic ductal adenocarcinoma (PDAC) cells, associated with poor prognosis in PDAC patients." (PMID 33891561, 2021). "In pancreatic ductal adenocarcinoma (PDAC) and acute myeloid leukemia, high COMMD7 expression is associated with a poor prognosis." (PMID 36776284, 2023). "A recent study claimed that COMMD7 overexpression positively correlated with histological differentiation and tumor node metastasis (TNM) stage of pancreatic ductal adenocarcinoma (PDAC), and PDAC patents with higher COMMD7 expression tended to have poorer overall survival rates." (PMID 33273919, 2020).
acute myelogenous leukemia (3 papers, 2021 to 2025). "Shao's research depicts that the transcription factor ZNF460 regulates COMMD7 and impacts acute myeloid leukaemia (AML) progression via the NF‐κB signalling pathway." (PMID 40521987, 2025). "By comparing the expression of COMMD7 normal samples in TCGA and GTEX database and corresponding tumor samples in TCGA database, COMMD7 was found significantly high expressed in 28 types of cancer, including acute myelogenous leukemia (LAML)." (PMID 33891561, 2021).
gastric cancer (3 papers, 2012 to 2023). A primary or metastatic malignant neoplasm involving the stomach. "COMMD7 is associated with cisplatin resistance in gastric cancer." (PMID 36776284, 2023). "Recently, Cao and colleagues found that abnormal expression of COMMD7 has an important role in gastric cancer." (PMID 37057209, 2023). "In gastric cancer, the activation of the Linc00852/miR-514a-5p/COMMD7 axis enhances cisplatin resistance." (PMID 36776284, 2023). "Our preliminary studies show that COMMD7 is extensively overexpressed in multiple gastrointestinal malignancies, including HCC, gastric carcinoma, cholangiocarcinoma, and colon carcinoma." (PMID 23049798, 2012).
colon carcinoma (2 papers, 2012 to 2020). "It is observed that one overlap, i.e., COMMD7 (COMM domain containing 7) existed in the MEGs for colon and esophageal cancer, whereas the other overlap, i.e., HAND2 (heart and neural crest derivatives Expressing 2) existed in the MEGs for colon cancer and NSCLC." (PMID 33273919, 2020).
leukemia (1 paper, 2021). A malignant (clonal) hematologic disorder, involving hematopoietic stem cells and characterized by the presence of primitive or atypical myeloid or lymphoid cells in the bone marrow and the blood. "Here, COMMD7 was found to be associated with these pathways and may be involved in the genesis and maintenance of leukemia cells, calling for further studies to confirm our results and explore the specific regulatory mechanism of COMMD7 as well as these pathways." (PMID 33891561, 2021).
myocardial infarction (1 paper, 2021). Gross necrosis of the myocardium, as a result of interruption of the blood supply to the area, as in coronary thrombosis. "Furthermore, an association study of several of these genes showed a putative association with myocardial infarction for COMMD7 (COMM domain-containing protein 7) and a highly significant association for LRRFIP1 (leucine-rich repeat (in FLII) interacting protein 1)." (PMID 33725119, 2021).
pancreatic cancer (1 paper, 2017). "Testing additional patient‐derived pancreatic cancer cells reveals particular genes (ITGA1,TNFAIP2,COMMD7,RAB3D) that respond to APE1 knockdown similarly across all the cell lines." (PMID 28922540, 2017).
rheumatoid arthritis (1 paper, 2022). A chronic, systemic autoimmune disorder characterized by inflammation in the synovial membranes and articular surfaces. "We use molecular interaction and colocalisation analyses to identify multiple nuclear regulatory pathways linking meQTL loci to phenotypic variation, including UBASH3B (body mass index), NFKBIE (rheumatoid arthritis), MGA (blood pressure), and COMMD7 (white cell counts)." (PMID 34980917, 2022).
cancer (7 papers, 2016 to 2024). A tumor composed of atypical neoplastic, often pleomorphic cells that invade other tissues. "In addition, COMMD7 was strongly associated with the patients’ individual cancer stage and tumor grade." (PMID 34493238, 2021). "Expression of TBCA, COMMD7, LSM4, and FKBP1A were significantly lower in the cancer tissues than the normal tissues." (PMID 39012280, 2024). "COMMD7, ITGA1, RAB3D, and TNFAIP2 have all been shown to be upregulated in various cancers including PDAC." (PMID 28922540, 2017).
tumor (7 papers, 2012 to 2023). "COMMD7 is a member of the COMMD family, which is overexpressed in HCC and associated with tumor growth and invasion." (PMID 27129158, 2016). "COMMD7 knockdown also exhibited an antineoplastic effect in vivo, which manifested as tumor xenograft growth retardation." (PMID 23049798, 2012). "Our clinicopathological analysis has shown that COMMD7 is overexpressed in HCC and associated with advanced tumor staging and portal vein invasion, suggesting a poor prognosis in HCC patients." (PMID 23049798, 2012). "Consistent with the in vitro experiments, COMMD7 shRNA significantly retarded the xenograft tumor growth in vivo as compared to control shRNA and blank control." (PMID 23049798, 2012). "Our in vivo tumor xenograft experiment also suggests that COMMD7 contributes significantly to tumor cell proliferation and apoptosis in vivo." (PMID 23049798, 2012). "Immunohistochemistry revealed less Ki67-positive tumor cells in the COMMD7 shRNA-treated group, indicating COMMD7 shRNA inhibited cell proliferation in vivo." (PMID 23049798, 2012). "The measurements of xenograft tumor volumes showed that the size of tumor deriving from COMMD7 shRNA-treated cells was significantly smaller than those from control cells throughout four weeks of xenotransplantation." (PMID 23049798, 2012). "The down-regulation of COMMD7 expression manifests as the reduction in cell proliferation, the increase in cell apoptosis, and the growth retardation of tumor xenograft in vivo." (PMID 23049798, 2012). "The effects of COMMD7 silencing on HepG2 cell proliferation in vitro and xenograft tumor growth in vivo were evaluated." (PMID 23049798, 2012). "Mounting evidence points to an influential role for COMMD7 in promoting tumor progression." (PMID 37057209, 2023). "Anti-tumor effects can be achieved by suppressing COMMD7 in PDAC cells." (PMID 37057209, 2023). "By downregulating cyclin D1, inhibiting MMP-2 secretion, and activating the ERK1/2 and apoptosis signaling pathways, inhibition of COMMD7 may reduce tumor growth and invasion." (PMID 36776284, 2023). "Given that COMMD7 has been reported associated with tumor progression in various human solid cancers but rarely reported in AML, herein, RNA sequencing data from TCGA and GTEx were obtained for analysis of COMMD7 expression and differentially expressed gene (DEG)." (PMID 33891561, 2021). "COMM domain-containing protein 7 (COMMD7), a member of the COMMD family defined by the presence of a conserved and unique motif termed the copper metabolism gene MURR1 (COMM) domain, which is located on chromosome 20q11.21, has been reported associated with tumor progression in human solid cancers." (PMID 33891561, 2021). "In this study, we aim to examine the effects of COMMD7 silencing on HCC cell proliferation in vitro and tumor growth in vivo." (PMID 23049798, 2012).
cardiovascular disease (2 papers, 2017 to 2018). "Several of these SNPs, such as rs6141803 of COMMD7 and rs41316468 in PKT2B, have independently confirmed associations with cardiovascular diseases (CVDs) according to other unrelated studies, suggesting that our pipeline is robust in identifying key genetic variants." (PMID 28441463, 2017).
infection (1 paper, 2024). The state of being infected such as from the introduction of a foreign agent such as serum, vaccine, antigenic substance or organism. "Proteins associated with any persistent symptom attributed to long COVID at ten months post-infection included FKBP7, which accelerates the folding of proteins during protein synthesis, and COMMD7, which associates with the NF-kappa-B complex and suppresses its transcriptional activity." (PMID 39324144, 2024).
COMMD7 also shares sentences with these, for which no sentence is quoted: cholangiocarcinoma (1 paper); colorectal cancer (1); esophageal cancer (1); lung carcinoma (1); malignant melanoma (1); non-small cell lung carcinoma (1); renal cell carcinoma (1); thrombosis (1).